FOXD1 (forkhead box D1)
Diseases named in the same sentence as FOXD1 in open-access papers (continued):
Sharing a sentence is not in itself a finding about the gene and the disease.
cancer (continued). "Therefore, FOXD1 plays important roles in many cancers, such as proliferation, metastasis, and drug resistance, but some cancers are on the contrary." (PMID 35607308, 2022). "We first assessed the FOXD1 expression in pan-cancer data of TCGA." (PMID 34028536, 2021). "Moreover, FOXD1 expression in HNSC occurred mainly in the nucleus, and FOXD1 expression was significantly increased in cancer tissues compared with corresponding adjacent normal tissues." (PMID 34269372, 2021). "The forkhead transcription factor FOXD1 plays an essential role in kidney development, and because developmental programs are frequently misregulated in cancer, we were interested to know what role it plays in cancer of the adult kidney, specifically ccRCC which is the most common form." (PMID 33761914, 2021). "Moreover, GSEA revealed that FOXD1 was mainly involved in cancer-related signaling pathway and metabolism-related pathways." (PMID 34269372, 2021). "FOXD1 has been reported to function as an oncogene in several types of cancer." (PMID 33403027, 2021). "Previous findings have shown the clinical significance of FOXD1 abundance in various human cancers." (PMID 34772357, 2021). "Among which, FOXD1 has been identified to have critical influence in human cancers." (PMID 32669972, 2020). "Previously, studies have reported that FOXD1 could activate ERK signaling to accelerate cancer development." (PMID 32669972, 2020). "Moreover, increased cancer cell migration and invasion ability are consistent with the FOXD1-overexpression models." (PMID 31795213, 2019). "However, the precise role of FOXD1 in cancer progression remains largely unexplored." (PMID 40083705, 2025). "Finally, we predicted FOXD1 may be involved in many immune-related biological functions and cancer-related signaling pathways." (PMID 35607308, 2022). "As a core member of the human FOX gene family, FOXD1 expression may be an oncogene involving cancer progression and has been critically participated in cell migration and apoptosis, cancer stem cell self-renewal as well as other physiological and pathological processes." (PMID 34772357, 2021). "As expected, the present findings suggested that FOXD1 plays a major role in mediating senescence by suppressing p21 in HNSCC, thus providing novel therapeutic strategies for cancer treatment." (PMID 37563111, 2023). "However, it remains unknown whether FOXD1 regulates the senescence of cancer cells." (PMID 37563111, 2023). "FOXD1, as a newly discovered FOX family transcriptional factor, played a controversial role in varied cancer types." (PMID 34269372, 2021). "Moreover, many cancer-related pathways and metabolism-related processes may be regulated by FOXD1." (PMID 34269372, 2021). "To explore the cancer-promoting effects in HNSCC, we first examined the FOXD1 abundance in several HNSCC cell lines and carried out the loss-of-function assay by siRNA modulated knockdown." (PMID 34772357, 2021). "We further analyzed the relationship of FOXD1 with TMB and immunosuppressive genes using TCGA pan-cancer data." (PMID 34028536, 2021). "As the interaction of Gal-3 with integrins promotes cancer progression, and integrins are one of the ERK upstream effectors, we next investigated whether FOXD1 expression is regulated by the Gal-3/ITGβ1/ERK axis." (PMID 31795213, 2019). "Genes coding for proteins supporting cancer cells survival or proliferation such as FOXD1 or EIF5A appeared up-regulated in resistant and not in sensitive, while E-cadherin, CLDN7, MDK, PKDCC, and JAG1 were more down-regulated." (PMID 27835869, 2016). "However, the role of FOXD1 in regulating cancer development under hypoxia conditions has not been reported." (PMID 41214670, 2025). "The biological function of FOXD1 in human cancers has not been completely explored." (PMID 34269372, 2021).
kidney disease (3 papers, 2016 to 2023). "To identify lncRNAs that are involved in the myofibroblastic response of pericytes in fibrotic kidney disease, we profiled lncRNAs from FoxD1-derivative interstitial cells that were isolated from injured and contralateral control kidneys." (PMID 30914951, 2019).
infection (2 papers, 2018 to 2019). The state of being infected such as from the introduction of a foreign agent such as serum, vaccine, antigenic substance or organism. "High expression levels of YAP and FOXD1 were detectable by RT-qPCR; immunohistochemical analysis of the flag-tagged Luc, YAP, and FOXD1 further verified the persistent infection of the lentiviruses and expression of indicated proteins primarily in the superficial zone of articular cartilage." (PMID 30933975, 2019).
degenerative diseases (1 paper, 2019). "Overexpression of YAP or FOXD1 delayed replicative and pathological senescence, implying a therapeutic potential of targeting the YAP–FOXD1 axis to relieve aging-associated degenerative diseases." (PMID 30933975, 2019).
digestive system tumors (1 paper, 2024). "It has been reported that 17 genes play a key role in digestive system tumors, of which three are in the FOX family (FOXD1, FOXM1, and FOXQ1)." (PMID 38839744, 2024).
FOXD1 also shares sentences with these, for which no sentence is quoted: nasopharyngeal carcinoma (5 papers); esophageal cancer (3); colon adenocarcinoma (2); renal fibrosis (2); sarcoma (2); uveal melanoma (2); asthma (1); bladder urothelial carcinoma (1); brain cancer (1); breast invasive carcinoma (1); cervical squamous cell carcinoma (1); cholangiocarcinoma (1); chronic kidney disease (1); COVID-19 (1); cutaneous melanoma (1); diffuse large B-cell lymphoma (1); digestive system carcinoma (1); endocervical adenocarcinoma (1); endometriosis (1); epidermal cysts (1); heart diseases (1); Hodgkins lymphoma (1); hypopharynx tumor (1); Infertility (1); kidney (1); laryngeal squamous cell carcinoma (1); larynx tumor (1); leukemia (1); liver cancer (1); mesothelioma (1).
A further 15 diseases each share a sentence with FOXD1 in 1 paper.